C9orf72 (C9orf72-SMCR8 complex subunit)
Diseases named in the same sentence as C9orf72 in open-access papers (continued):
Sharing a sentence is not in itself a finding about the gene and the disease.
frontotemporal dementia (continued). "Its association with amyotrophic lateral sclerosis/frontotemporal dementia (ALS/FTD) spectrum diseases has been fully established, although a causative role for C9ORF72 in Alzheimer's disease (AD) and Parkinson's disease (PD) remains to be established." (PMID 33390807, 2021). "Expansion of the hexanucleotide repeat (HR) in the first intron of the C9orf72 gene is the most common genetic cause of amyotrophic lateral sclerosis (ALS) and frontotemporal dementia (FTD) in Caucasians." (PMID 33780440, 2021). "G4C2 repeat expansions within the C9orf72 gene are the most common genetic cause of amyotrophic lateral sclerosis (ALS) and frontotemporal dementia (FTD)." (PMID 33739284, 2021). "An intronic GGGGCC (G4C2) hexanucleotide repeat expansion (HRE) in the C9ORF72 gene is the most common cause of amyotrophic lateral sclerosis (ALS) and frontotemporal dementia (FTD), referred to as C9ALS/FTD." (PMID 33726839, 2021). "A hexanucleotide repeat expansion of C9orf72 is translated to dipeptide repeat proteins in amyotrophic lateral sclerosis and frontotemporal dementia patients." (PMID 34654821, 2021). "Although ALS is considered a motor neuron disease, there are cases of frontotemporal dementia (FTD) most possibly associated with the abnormalities within the C9orf72 (chromosome 9 open reading frame 72) gene, which contains repeat expansion of hexanucleotide GGGGCC." (PMID 34359973, 2021). "In 2011, abnormal GGGGCC hexanucleotide repeat expansion (HRE) within the C9orf72 gene was identified as a new cause of ALS and frontotemporal dementia (FTD)." (PMID 33477509, 2021). "Hexanucleotide GGGGCC repeat expansion in the C9ORF72 gene can cause toxic accumulation of dipeptide repeat (DPR) proteins, which is a common cause of amyotrophic lateral sclerosis (ALS) and frontotemporal dementia (FTD)." (PMID 33627125, 2021). "This is important in neurodegeneration, since frontotemporal dementia (FTD) and ALS-associated C9orf72 hexanucleotide expansion is implicated in autophagy, as will be detailed below." (PMID 34827556, 2021). "Several long-read sequencing technologies have been successfully tested also for the detection of the exanucleotide repeat expansion in C9orf72 gene which is the most common genetic cause of ALS and frontotemporal dementia (FTD)." (PMID 33919863, 2021). "The C9orf72 repeat expansion is the most common genetic cause of amyotrophic lateral sclerosis (ALS) and/or frontotemporal dementia (FTD)." (PMID 31858749, 2020). "One example is the GGGGCC hexanucleotide repeat expansion in the C9orf72 gene, which is associated with both ALS and frontotemporal dementia (FTD)." (PMID 32899160, 2020). "In addition to ALS, the role of C9orf72 was also identified as the major genetic cause of frontotemporal dementia (FTD) and FTD-ALS." (PMID 32848579, 2020). "ALS is associated with several genes, for example, C9ORF72, TARDBP, SOD1 and FUS, with some genes also contributing to the presence of frontotemporal dementia (FTD)." (PMID 33094283, 2020). "A repeat expansion mutation in the C9orf72 gene causes amyotrophic lateral sclerosis (ALS), frontotemporal dementia (FTD), or symptoms of both, and has been associated with gray and white matter changes in brain MRI scans." (PMID 33329355, 2020). "A mutation in the C9orf72 gene is the most common known cause of amyotrophic lateral sclerosis (ALS) and frontotemporal dementia (FTD)." (PMID 33013410, 2020). "Repeat expansion mutations in the gene C9orf72 are the most common genetic cause of ALS and frontotemporal dementia (FTD) in the United States." (PMID 32769055, 2020). "A mutation in the C9orf72 gene has been linked to the most common forms of neurodegenerative diseases that include amyotrophic lateral sclerosis (ALS) and frontotemporal dementia (FTD)." (PMID 32282804, 2020). "The hexanucleotide repeat expansion in intron 1 of the C9orf72 gene causes amyotrophic lateral sclerosis (ALS) and frontotemporal dementia." (PMID 33168078, 2020).
frontotemporal dementia (continued). "A GGGGCC hexanucleotide repeat expansion (HRE) in C9orf72 is the most common known cause of amyotrophic lateral sclerosis (ALS) and is also a major cause of frontotemporal dementia (FTD) and the ALS/FTD overlap syndrome." (PMID 32119645, 2020). "The expanded GGGGCC hexanucleotide repeat in the non-coding region of the C9orf72 gene is the most common genetic cause of amyotrophic lateral sclerosis (ALS) and frontotemporal dementia (FTD)." (PMID 32983232, 2020). "C9orf72 repeat expansion is the major genetic cause of familial amyotrophic lateral sclerosis (ALS) and frontotemporal dementia (FTD)." (PMID 32620797, 2020). "A hexanucleotide repeat expansion in a noncoding region of C9orf72 is the most common genetic cause of amyotrophic lateral sclerosis (ALS) and frontotemporal dementia (FTD)." (PMID 31651360, 2019). "This expansion, which represents the most common genetic cause of frontotemporal lobar degeneration (FTLD) and motor neuron disease (MND), results in a loss of C9orf72 expression and the generation of RNA foci and dipeptide repeat (DPR) proteins." (PMID 31594549, 2019). "In 2011, two independent studies demonstrated that the most common cause of familial forms of Frontotemporal Dementia (FTD) and/or Amyotrophic Lateral Sclerosis (ALS) is the expansion of hexanucleotide repeats within the C9orf72 gene." (PMID 30610612, 2019). "Repeat primed-PCR and subsequent fragment analysis is widely used to detect repeat expansions, such as the repeat expansion in the C9orf72 locus implicated in both Amyotrophic Lateral Sclerosis (ALS) and Frontotemporal Dementia (FTD)." (PMID 30284037, 2019). "A GGGGCC hexanucleotide repeat expansion within the C9orf72 gene is the most common genetic cause of both amyotrophic lateral sclerosis (ALS) and frontotemporal dementia (FTD)." (PMID 30604225, 2019). "Mutations in C9orf72 are the most common cause of familial ALS and frontotemporal dementia (FTD) and are linked with impairments in synapse formation, morphology, and function [54•]." (PMID 31440934, 2019). "The G4C2-repeat expansion in C9orf72 is the most common known cause of amyotrophic lateral sclerosis (ALS) and frontotemporal dementia (FTD) in Caucasians." (PMID 30252044, 2018). "The C9orf72 mutation (C9+) is also a common cause of familial frontotemporal dementia (FTD)." (PMID 30568632, 2018). "Intronic hexanucleotide repeat expansions in C9orf72 are the most common cause of familial amyotrophic lateral sclerosis (ALS) and frontotemporal dementia (FTD), two disease conditions that are often co-morbid [6•, 8]." (PMID 30291526, 2018). "A GGGGCC hexanucleotide repeat expansion in the first intron of the C9orf72 gene is the most common genetic defect associated with amyotrophic lateral sclerosis (ALS) and frontotemporal dementia (FTD) (C9ALS/FTD)." (PMID 27768524, 2018). "The recent discovery of a pathogenic expansion of a (GGGGCC)n repeat in the C9orf72 gene in amyotrophic lateral sclerosis (ALS) and frontotemporal dementia (FTD) led to a burst of mechanistic discoveries." (PMID 29175945, 2018). "A hexanucleotide repeat expansion in the first intron/promoter region of C9orf72 is the most common genetic cause of amyotrophic lateral sclerosis (ALS) and frontotemporal dementia (FTD)." (PMID 30533567, 2018). "The GGGGCC repeat expansion in the C9orf72 gene was recently identified as a major cause of amyotrophic lateral sclerosis (ALS) and frontotemporal dementia (FTD) in several European populations." (PMID 30550541, 2018). "A GGGGCC repeat expansion mutation in C9ORF72 is the most commonly known genetic cause of ALS and frontotemporal lobar degeneration (FTLD/FTD)." (PMID 29950492, 2018). "Expanded GGGGCC repeats in the first intron of the C9orf72 gene represent the most common cause of familial amyotrophic lateral sclerosis (ALS) and frontotemporal dementia (FTD)." (PMID 28072389, 2017).
frontotemporal dementia (continued). "Genetic frontotemporal dementia is most commonly caused by mutations in the progranulin (GRN), microtubule-associated protein tau (MAPT) and chromosome 9 open reading frame 72 (C9orf72) genes." (PMID 28529873, 2017). "Hexanucleotide repeat expansion (G4C2) in the first intron of the C9orf72 gene is the most common genetic cause of amyotrophic lateral sclerosis (ALS) and frontotemporal dementia (FTD)." (PMID 28973350, 2017). "A (ggggcc)n hexanucleotide repeat expansion upstream of the coding region of C9orf72 is the most common genetic cause of amyotrophic lateral sclerosis (ALS) and frontotemporal dementia (FTD), with some patients showing symptoms of both diseases." (PMID 28409281, 2017). "A pathological GGGGCC hexanucleotide repeat expansion mutation located within the non-coding portion of the C9ORF72 gene has been identified as the cause of chromosome 9p21-linked ALS and frontotemporal dementia (FTD)." (PMID 28606110, 2017). "Although the function of the C9ORF72 gene product is unclear, C9ORF72 is so far the most commonly mutated gene in familial ALS and frontotemporal dementia (FTD)." (PMID 28587229, 2017). "The possibility of treatment with ASOs that reduce pathogenic splice variants of C9orf72 is also under investigation for the treatment of amyotrophic lateral sclerosis (ALS) and frontotemporal dementia (FTD)." (PMID 28982376, 2017). "Hexanucleotide repeat expansions (HREs) in C9orf72 are regarded as the most common genetic cause of the progressive neurodegenerative diseases, amyotrophic lateral sclerosis (ALS) and frontotemporal dementia (FTD)." (PMID 28550099, 2017). "A (G4C2)n repeat expansion in C9ORF72 is the most common genetic cause of ALS and frontotemporal dementia (FTD)." (PMID 28158451, 2017). "A pathogenic hexanucleotide repeat expansion within the C9orf72 gene has been identified as the major cause of two neurodegenerative syndromes, amyotrophic lateral sclerosis (ALS) and frontotemporal dementia (FTD)." (PMID 28522837, 2017). "Here, we analyze the dipeptide repeat (DPR) proteins that form neuronal inclusions in patients with hexanucleotide repeat expansion C9orf72, the most common known cause of amyotrophic lateral sclerosis (ALS) and frontotemporal lobar degeneration (FTLD)." (PMID 28351931, 2017). "The presence of hexanucleotide repeat expansion (HRE) in the first intron of the human C9orf72 gene is the most common genetic cause underlying both familial amyotrophic lateral sclerosis (ALS) and frontotemporal dementia (FTD)." (PMID 28729824, 2017). "Hexanucleotide repeat expansions in C9orf72 are the most common inherited cause of amyotrophic lateral sclerosis (ALS) and frontotemporal dementia (FTD)." (PMID 27776165, 2016). "GGGGCC hexanucleotide repeat expansions in C9ORF72 represent the most common genetic variant of amyotrophic lateral sclerosis (ALS) and frontotemporal dementia (FTD)." (PMID 25943887, 2015). "An intronic GGGGCC-repeat expansion of C9ORF72 is the most common genetic variant of amyotrophic lateral sclerosis (ALS) and frontotemporal dementia." (PMID 26016851, 2015). "Patients with pathologic hexanucleotide repeat expansions in C9orf72, a gene linked to amyotrophic lateral sclerosis (ALS) and frontotemporal dementia (FTD), can rarely demonstrate clinical and neuroimaging features indistinguishable from MSA." (PMID 26501269, 2015). "Hexanucleotide repeat expansion in C9orf72 is the most common pathogenic mutation in patients with amyotrophic lateral sclerosis (ALS) and frontotemporal lobar degeneration (FTLD)." (PMID 25120191, 2014). "A massive expansion of the GGGGCC hexanucleotide repeat in the intron between non-coding exons 1a and 1b of the chromosome 9 open reading frame 72 (C9orf72) gene was recently found to be a major genetic cause of familial frontotemporal dementia (FTD) and amyotrophic lateral sclerosis (ALS)." (PMID 24803912, 2014).
frontotemporal dementia (continued). "Marked frontotemporal grey matter changes have been observed in those with frank frontotemporal dementia, and in those ALS cases linked to C9orf72 hexanucleotide repeat expansions, known to have consistent cognitive impairments." (PMID 24951638, 2014). "The expansion of a (G4C2)n repeat within the human C9orf72 gene has been causally linked to a number of neurodegenerative diseases, most notably familial amyotrophic lateral sclerosis (ALS) and frontotemporal dementia (FTD)." (PMID 25207541, 2014). "Expansion of GGGGCC repeats in C9orf72 causes familial amyotrophic lateral sclerosis (ALS) and frontotemporal dementia, but the underlying mechanism is unclear." (PMID 24866055, 2014). "Since this tool was developed, pathological expansion in the C9orf72 gene has been identified as a cause of ALS and frontotemporal dementia." (PMID 23755159, 2013). "This locus was previously found to be one of the linked loci in families with ALS and frontotemporal dementia (FTD), and it was recently shown that a hexanucleotide repeat expansion in C9orf72 was the basis of this linkage signal." (PMID 22509407, 2012). "Another novel DENN protein identified in this study is C9ORF72; expansions of the hexanucleotide GGGGCC in its first intron have been recently implicated in amyotrophic lateral sclerosis (ALS) and fronto-temporal dementia (FTD)." (PMID 23248642, 2012). "We also emphasize the importance of the amyotrophic lateral sclerosis and frontotemporal dementia communities working together in partnership with the C9orf72 repeat expansion carrier community, the regulatory authorities and the broader drug development community." (PMID 40794569, 2025). "The gene variants of C9orf72 and hexanucleotide repeat (GGGGCC) expansion (HRE) have been considered the most common genetic defects of familial ALS, accounting for about 20–25% of familial cases and frontotemporal dementia." (PMID 40362512, 2025). "Furthermore, brain organoids have been utilized to investigate changes in cellular architecture and connectivity and molecular pathological characteristics in patients with C9orf72-mediated ALS/frontotemporal dementia (FTD)." (PMID 41359105, 2025). "A pathological hexanucleotide repeat expansion (GGGGCC), in the intronic region of the C9orf72 locus—exceeding 30 repeats—is the most common genetic cause of familial autosomal dominant amyotrophic lateral sclerosis (ALS) as well as frontotemporal dementia (FTD) with ALS." (PMID 40722695, 2025). "Furthermore, synaptic loss has been detected in presymptomatic carriers of a mutation in C9orf72, which is the gene most strongly associated with familial ALS and frontotemporal dementia." (PMID 40707625, 2025). "The responsible pathogenic mutation usually resides in one of the three major genes causing frontotemporal dementia: progranulin (GRN) (the most frequent genetic cause), chromosome 9 opening reading frame 72 (C9orf72) or (rarely) microtubule-associated protein tau (MAPT)." (PMID 37906327, 2024). "Importantly, C9ORF72 mutations are also known to cause frontotemporal dementia (FTD)." (PMID 38605366, 2024). "Expanded hexanucleotide GGGGCC repeats in the first intron of C9orf72 gene are the main genetic cause of the neurodegenerative diseases amyotrophic lateral sclerosis (ALS) and frontotemporal dementia (FTD) and are the most common cause of familial ALS and FTD within Europe and North America3–6." (PMID 37717009, 2023). "Annualized rate of change in blood neurofilament light may distinguish frontotemporal dementia-GRN and -C9orf72 mutation subtypes and provide prognostic value, especially in combination with other pathophysiological and topographic biomarkers." (PMID 36694576, 2023). "In this review, we summarize our current understanding of abnormal repeat RNA metabolism and repeat-associated non-AUG translation in C9orf72 frontotemporal lobar degeneration/ALS." (PMID 36793534, 2023).
frontotemporal dementia (continued). "The G4C2 hexanucleotide repeat expansion in the c9orf72 gene is a major genetic cause of familial amyotrophic lateral sclerosis (ALS) and frontotemporal lobar degeneration (FTLD), with the formation of G-quadruplexes directly linked to the development of these diseases." (PMID 37686239, 2023). "At the gene level, hypermethylation of the promoter for C9orf72, a gene responsible for the majority of the FALS cases (as well as for those of frontotemporal dementia), correlates with its reduced mRNA expression levels in a clinical cohort of C9orf72 pathological expansion carriers." (PMID 36293477, 2022). "Many RNA repeats form unusual secondary structures that have a wide range of biological or pathological effects, such as CAG and CUG hairpins in polyglutamine diseases and DM1, respectively, and GGGGCC G-quadruplex in C9orf72-ALS/FTD (amyotrophic lateral sclerosis/frontotemporal dementia)." (PMID 35563872, 2022). "Interestingly, C9orf72 repeat expansions of intermediate length, a mutation often found in cases of familial ALS and frontotemporal dementia (FTD), have been associated with severe COVID-19 requiring mechanical ventilation." (PMID 35434769, 2022). "Familial hexanucleotide GGGGCC repeat expansion in the C9orf72 gene accounts for a third of familial amyotrophic lateral sclerosis and a quarter of frontotemporal dementia (FTD) cases, leading to its haploinsufficiency and inducing the formation of RNA-rich nuclear aggregates." (PMID 35625878, 2022). "Another aspect of C9orf72 that could contribute towards the development biomarkers for frontotemporal dementia and amyotrophic lateral sclerosis is the study of methylation of G4C2 hexanucleotide repeat." (PMID 35202463, 2022). "Most notably, the understanding of frontotemporal dementia has been further advanced by the identification of disease causing mutations in the genes for TAR DNA-binding protein-43 (TARDBP), progranulin (GRN) and C9orf72-SMCR8 complex subunit (C9ORF72)." (PMID 35120450, 2022). "screened for C9orf72 mutations in 398 patients with clinical presentations of frontotemporal dementia and found one patient who had CBD pathology without TDP‐43 pathology." (PMID 34823271, 2022). "Amyotrophic lateral sclerosis (ALS) and frontotemporal dementia (FTD) are progressive neurodegenerative diseases, whose most frequent genetic cause is hexanucleotide repeat (HR) expansion from normal 2 to 20 repeats to pathological hundreds of repeats within a non-coding region of the C9orf72 gene." (PMID 33780440, 2021). "The most frequent cause of familial Amyotrophic Lateral Sclerosis (ALS) and Frontotemporal Dementia (FTD) are hexanucleotide repeat expansions in the non-coding region of the C9ORF72 gene that are translated into five dipeptide repeat (DPR) proteins." (PMID 34099711, 2021). "Frontotemporal dementia (FTD) and amyotrophic lateral sclerosis (ALS) are considered to be part of a disease spectrum most often caused by a non-coding hexanucleotide GGGGCC repeat expansion in the C9orf72 gene." (PMID 33168090, 2020). "Frontotemporal dementia (FTD) and amyotrophic lateral sclerosis (ALS)-associated C9orf72 is implicated in autophagy, but whether it activates or inhibits autophagy is partially controversial." (PMID 31658762, 2019). "Thus, RAN translation producing toxic dipeptide repeats was measured in lymphoblasts of patients with C9orf72-associated ALS and frontotemporal dementia." (PMID 30483310, 2018). "Then, we wondered whether poly-GR/PR inclusions in patients could be labeled by stress granule markers and compared an frontotemporal lobar degeneration case with C9orf72 repeat expansion with a healthy control case by double immunofluorescence." (PMID 30456350, 2018).